CCL5 (C-C motif chemokine ligand 5)
Diseases named in the same sentence as CCL5 in open-access papers (continued):
Sharing a sentence is not in itself a finding about the gene and the disease.
viral infection (continued). "The miR-US5-1/miR-UL112-3p mutant virus infection resulted in increased secretion of IL-6, CCL5, and TNF-α (in THP-1 cells) compared to WT-infected cells, which was significantly reduced in cells infected with the miRNA mutant virus expressing shRNAs targeting IKKα and IKKβ." (PMID 28270578, 2017). "To explore whether this observation was specific to these 3 donors or an inherent property of the viral strains, we screened MDMs from an additional 16 donors for induction of IL-6 and CCL5 during viral infection." (PMID 28877226, 2017). "CCL5 is an important chemokine during immune responses against viral infections." (PMID 24910790, 2014). "Therefore, any alteration in CCR5 and CCL5 expression can lead to imperfect immune responses against viral infection, especially HBV infection." (PMID 24910790, 2014). "Thus, the C6 protein significantly reduced the expression of IFN-β and CCL5 after stimulation of PRRs by ligands or viral infection." (PMID 21931555, 2011). "However, in goat SMGs, we found that the significantly upregulated TCONS_00020715 trans targeted gene CCL5 was negatively correlated, which seems to indicate that the ability of goat SMGs to initiate related signaling pathways through CCL5 to cope with viral infection is weakened with age." (PMID 36672927, 2023). "Our results indicate that IEC might selectively regulate CCL20, CXCL10 and CCL5 in order to restrict the propagation of the viral infection and the subsequent tissue damage, thus promoting local clearance of the virus and facilitating re-establishment of tissue homeostasis." (PMID 36142892, 2022). "Additionally, the CCL5/CCR5 axis is also involved in viral infections." (PMID 35702353, 2022). "We also noticed that the expression of Ccl5 and Il12a/Il12p70 reached the peak on 5 d.p.i., which could reflect the activation of T and natural killer (NK) cells during viral infection (p = 0.0050 for Ccl5 in C57BL/6, p < 0.0001 for Il12a/Il12p70 in BALB/c and C57BL/6)." (PMID 34907154, 2021). "Furthermore, the production of Ifnb, Isg15, and Ccl5 was increased in Arrb2−/− mouse embryonic fibroblasts (MEFs) transfected with K171R mutant compared with WT β-arrestin 2, whereas K171Q mutant abolished the positive regulation during virus infection." (PMID 33243993, 2020). "For example, chemokine (C-C motif) ligand 5 (CCL5), also known as RANTES, previously reported to be genetically associated with asthma, is differentially expressed between asthmatic and non-asthmatic cultures at both baseline (p = 0.026) and post viral infection (p = 0.047)." (PMID 25706956, 2015). "First, we analyzed the production of IFNB, ISG54, and CCL5 in USP5-overexpressed and USP5-/- A549 cells after viral infection." (PMID 39761299, 2025). "Virus infection typically results in an upregulation of chemokines (CCL2 and CCL5) and alterations in tight junction protein expression, thereby modifying endothelial cell function and increasing vascular permeability." (PMID 39021576, 2024). "We also analyzed cytokines and chemokines related to DC function and the control of viral infection, finding differences in IP10, IL12, CCL5, MIP-1α, and MIP-1β." (PMID 36851164, 2023). "The results showed that phillyrin treatment alleviated pneumonia induced by virus infection and significantly ameliorated the upregulation of multiple pro-inflammatory cytokines and chemokines (e.g., IL-1β, CXCL1, CCL3, CCL2, CCL5 and so on) in BALF." (PMID 37957672, 2023). "In viral infections, inhibiting the expression of miR-369-3p dramatically reduces the expression of antiviral response genes, including CCL3, CCL5, CTSS, CXCL11, and IRF3." (PMID 37509488, 2023). "Differences between samples from controls and neonates with ongoing viral infection in several molecules (filaggrin, VEGF, RANTES (CCL5), HIF-1α, IL-17A and IL-1 β) were also observed, indicating an immune response associated with viral infection." (PMID 36482106, 2022).
viral infection (continued). "Real-time quantitative PCR (qRT-PCR) verified that the chemokine CCL2, CCL3, and CCL5 expression levels gradually increased with prolonged viral infection (MOI, 0.5), with the increase in CCL5 expression the most obvious." (PMID 36317881, 2022). "Chiefly amongst these, CCL3 (macrophage inflammatory protein-1α; MIP-1α), CCL4, CCL5, CXCL8, and CXCL10 are broadly expressed in the context of several (murine/human) viral infections." (PMID 34835105, 2021). "We showed that the inhibition of BCLXL specifically induces apoptosis and impaired production of CCL5 and CXCL10, which are ligands for CCR5 and CXCR3, respectively, during in vitro and in vivo viral infections." (PMID 30261081, 2018). "Like IFN responses, with low MOI value, also CXCL10, CCL5, and TNF-α responses were higher in H5N1-infected Mɸs with low MOI value than with low MOI values in H3N2 or H7N9 virus infection." (PMID 30065728, 2018). "For FVC, statistically significant interactions between viral infection and inflammation were seen for CXCL10 mRNA, TLR3 mRNA, IL-4, IL-13, CCL5, CCL20 and CCL24." (PMID 30463560, 2018). "We observed increased level of inflammatory mediators (IL-1α, IL-1β, IL-6, MIP-1α (CCL3), MIP-1β (CCL4), RANTES (CCL5), MCP-1 (CCL2)) following H5N3 virus infection at 4, 8 and 20 hpi compared to cells infected with the H1N1/WSN, H5N2 and H9N2 viruses." (PMID 28558796, 2017). "On the other hand, chemokines CCL-5 and chemokine (C-X-C motif) ligand-10 (CXCL-10) moderately increased post-virus infection." (PMID 27446066, 2016). "Regulated upon activation, normal T cell expressed and secreted (RANTES, also named as CCL5), one of natural ligands for HIV-1 coreceptors, has been shown to play a role in immune responses to viral infections." (PMID 23577146, 2013). "Our data indicate that the induction of IL-6, IL-8, IL-10, CCL-5, as well as IFN-β, were apparent at the earliest stages of viral infection even before ERK1/2 was further activated." (PMID 22279582, 2012). "RANTES/CCL5 is an important proinflammatory chemokine that induces the recruitment of T cells (including CTLs), monocytes and eosinophils to the sites of virus infection." (PMID 21445235, 2011). "Additionally, CCL5, which is primarily expressed by T-cells and monocytes, is known to be induced by TNF-α and IFN-γ during pathogen infections, particularly viral infections." (PMID 39844283, 2025). "Interestingly, increased production of CCL5 and CXCL10 is also observed from CNS-resident cells following viral infections of the CNS, with CXCL10 linked to effector T cell trafficking to the CNS." (PMID 40613088, 2025). "In addition to being involved in the progression of multiple tumors, aberrant CCL5/CCR5 interactions have been identified in multiple types of inflammation, including AD, atherosclerosis, diabetes, hepatitis, and some viral infections." (PMID 35702353, 2022). "CCL5) that are known to respond to dsRNA, proinflammatory cytokines IL-6 and IL-8 that were shown to be suppressed by sEVs from TVV positive T. vaginalis, and IL-1β, a proinflammatory factor during viral infection." (PMID 35602021, 2022). "For both virus infections, expression of IFNB, IFNL, ISG56, MXA, and IP10 was merely less than 10-fold enhanced until 72 hours postinfection, while CCL5 expression was up-regulated up to 100-fold as compared to uninfected cells at 48 and 72 hours postinfection." (PMID 36383605, 2022). "SARS-CoV-2 Plpro antagonistic activity against ISG-15 might block the production of various cytokines involved in the activation of the innate immune response against viral infection, e.g., Type I IFN-β and chemokines such as CXCL10 and CCL5." (PMID 35891385, 2022). "Viral infections lead to inflammation of the lungs, via recruitment and production of neutrophils, eosinophils, CD4+ cells, CD8+ cells, and mast cells through increased expression and secretion of IL-6, IL-8, CXCL10/IP-10, CCL5/RANTES, and other cytokines." (PMID 34666750, 2021).
viral infection (continued). "In addition, viral infections act in concert with IL-13 to induce the release of chemokines crucial to eosinophilic inflammation, including CCL26 and CCL5, from bronchial epithelial cells." (PMID 32120846, 2020). "In our longitudinal study, we found that, in the absence of viral infection, CXCL10, IL-4, IL-13, CCL4, CCL5, CCL20 and CCL24 were each negatively associated with FVC." (PMID 30463560, 2018). "For example, in the absence of viral infection, CXCL10 mRNA, MDA5 mRNA, CXCL10, IL-4, IL-13, CCL4, CCL5, CCL20 and CCL24 were negatively associated with FVC." (PMID 30463560, 2018). "The addition of SAPS liposomes at various times following viral infection suppressed the release of the proinflammatory cytokines, CXCL8 and CXCL10, as well as the interferon-stimulated gene CCL5/RANTES from epithelial cell lines and normal and diseased primary human bronchial epithelial cells." (PMID 26906404, 2016). "CCL5 interaction with its receptor CCR5 provides an anti-apoptotic signal for macrophages during influenza virus infection and is important for cell survival during viral infections." (PMID 25566260, 2014). "Of these genes, only CCL5 was induced by bacteria after 12 h of incubation in the absence of virus infection." (PMID 24708855, 2014). "During viral infection, IRF3 and NF-κB co-operate to activate the IFN-β and the CCL5 promoters." (PMID 21931555, 2011). "Our results demonstrate that genes related to important immune pathways such as antigen presentation, inflammation, apoptosis and response to virus (Cxcl10, CxCl11, Ccl5, Ifr7, Ifi27 Oas1b, Fcerg1,Mif, Clusterin and MHC class II) were upregulated as a result of virus infection." (PMID 18558011, 2008). "However Elp3−/− cells upregulated Ccl5 to levels comparable with WT cells following PR8 viral infection, so not all host innate gene induction responses to IAV were Elongator-dependent." (PMID 41203129, 2025). "Nonetheless, the simultaneous increase in NK- and T-cells, up regulation of CCL5 by NK cells and increased expression of CCR1 and CCR5 receptors by microglia indicate a coordinated response across the innate and adaptive immune systems in response to peripheral viral infection." (PMID 39175524, 2024). "We subsequently validated by qPCR an increase in CCL5 mRNA in cerebelli of both males and females after PIC treatment and the number of CCL5+ cells detected by RNA-Scope® also increased equally in males and females, suggesting both sexes respond to viral infection with an increase in CCL5." (PMID 39175524, 2024). "To explore the effect of SPJ treatment on cytokine expression, we used real‐time PCR and observed that viral infection led to increased expression of cytokines and chemokines, including IL‐6, IL‐1β, TNF‐α, IL‐10, IFN‐α, IFN‐β, and IFN‐γ, as well as CXCL‐2, CXCL‐10, CCL‐2, CCL‐3, and CCL‐5." (PMID 37544014, 2023). "Cytokines associated with lung injuries, such as IL-1 and TNF-α could induce the production of several chemokines, such as CCL2, CCL3, CCL5, and CXCL8, culminating in a cytokine-to-chemokine-to-cytokine signaling cascade through inflammatory response to the viral infection." (PMID 36685603, 2022). "Moreover, CCL5 and CXCL10 are chemokines frequently released upon viral infection." (PMID 34386007, 2021). "Interestingly, viral infection also leads to reduced production of CXCL5, CCL5, CCL3, and GM-CSF, which are mainly involved in the attraction and activation of granulocytes and monocytes, suggesting that SARS-CoV-2 actively inhibits the recruitment of leukocytes early in infection." (PMID 33670363, 2021). "IP-10 and Ccl5 mRNA levels were also not increased by viral infection." (PMID 34249006, 2021). "As part of the innate immune response against virus infections targeting the respiratory tract, such as influenza virus or RSV infection, JEV infection of porcine NEC also induced several chemokines (CCL2, CCL5, and CXCL10), which would direct the migration of monocytes to the site of infection." (PMID 30282716, 2018).
viral infection (continued). "This series of experiments indicated that the induction of IL-6 and CCL5 by NH1125B is virus specific, requires viral infection and was not due to some other factor (e.g. virus) in the viral stock preparation." (PMID 28877226, 2017). "Viral infection also stimulated high levels of CCL3 and CCL5 production from microglia, but not from astrocyte cultures." (PMID 27207308, 2016). "In the setting of treatment before viral infection, SAPS treatment did not significantly alter HRV-1B-induced CXCL8 and CCL5 production." (PMID 26906404, 2016). "In contrast to non-cytopathic virus infection, our study suggests that the CNS innate response mechanism has a relatively higher-level synergy between MDA5, IRF1, CCL5, TNF-α, and IFN-γ to compensate for the IFN-I signaling loss to deal with a cytopathic virus infection." (PMID 32575459, 2020). "Indeed SAPS treatment before viral challenge with removal of liposomes immediately before viral infection further validates this conclusion, as it does not substantially diminish HRV-induced CXCL8 and CCL5 induction." (PMID 26906404, 2016).
atherosclerosis (138 papers, 2006 to 2025). A disease characterized by the build-up of fatty material and calcium deposition in the arterial wall resulting in partial or complete occlusion of the arterial lumen. "Research has demonstrated that both antagonism and deficiency of the CCR5/CCL5-axis attenuate atherosclerosis in advanced stages by decreasing lesion size, promoting plaque stability, and reducing monocyte, macrophage, and T cell infiltration." (PMID 38698438, 2024). "The pathogenic role of CXCL4 in accelerating atherosclerosis is mediated, in part, by augmenting the arrest of monocytes on endothelial cells in conjunction with CCL5 (RANTES)." (PMID 37255704, 2023). "C-C motif chemokine receptor 5 (CCR5) and its ligands CCL3 (MIP-1α), CCL4 (MIP-1β), and CCL5 (RANTES) also associate and contribute to the initiation and progression of atherosclerosis and related cardiovascular diseases." (PMID 36035865, 2022). "CCL5 has been associated with the progression of atherosclerosis, mediating smooth muscle cell activation and macrophage recruitment." (PMID 28072843, 2017). "Its genetic deletion accelerates atherosclerosis and is associated with elevated plasma levels of CCL5, an expansion of the platelet count, increase in MPV, and elevation of activation markers such as P-selectin, and leukocyte-platelet complexes." (PMID 25152735, 2014). "Peptides inhibiting the association of CXCL4 and CCL5 decrease atherosclerosis and macrophage content of lesions." (PMID 22807925, 2012). "The expression of CCL5 could promote the proliferation of SMCs and convert them into a synthetic phenotype that causes atherosclerosis, thereby promoting atherosclerosis." (PMID 36698075, 2023). "CCL5 (RANTES) is one of the CCR5 ligands that have been linked to atherosclerosis." (PMID 26688689, 2015). "Indeed genetic deletion of CCR5, an important receptor for CCL3/MIP1α and CCL5/RANTES, protected atherosclerotic prone mice from atherosclerosis and appeared to be associated with impaired Th1 immunity." (PMID 23029252, 2012). "Moreover, local CCL5 expression has been shown to closely associate with chronic inflammation in atherosclerosis." (PMID 22292067, 2012). "We hypothesised that the relevance of RANTES in the development of atherosclerosis should be reflected by associations between CCL5 genotypes, systemic RANTES levels as well as RANTES levels in atherosclerotic plaques and risk for coronary events." (PMID 22162987, 2011). "While CCL5/RANTES is thought to be crucial to monocyte recruitment during development of atherosclerosis high density lipoprotein may partly cause its cardioprotective effect by reducing circulating levels of CCL5/RANTES." (PMID 22011432, 2011). "The role of CCL5 in inflammation has also been inferred by an association between increased CCL5 protein expression and the degree of inflammation in a variety of disorders and pathologies, including neuropathic pain, asthma, atherosclerosis and arthritis among others." (PMID 29375328, 2017). "In CVDs, high levels of CCL5 have been demonstrated, identified in hyperlipidemia, atherosclerosis, and hypertension." (PMID 40859641, 2025). "Among individuals suffering from atherosclerosis, CCL5 is recognized as a potentially crucial factor in the reprogramming of myeloid cells." (PMID 40299531, 2025). "In the case of CXCL4•CCL5, a mouse CCL5-based synthetic cyclic peptide inhibitor called MKEY, which disrupts CCL5•CXCL4, has shown its efficacy by inhibiting atherosclerosis in Apoe-deficient mice fed a western-type diet." (PMID 37446102, 2023). "CCL5 is a member of the CC chemokine family participating in the regulation of the pro-inflammatory response by modulating immune cells in tissues and contributes to the pathogenic process of arterial damage and atherosclerosis, which in turn may be a precursor to the secondary ischemic damage." (PMID 37759440, 2023).